LHFPL5 (LHFPL tetraspan subfamily member 5)
Description:
Auxiliary subunit of the mechanotransducer (MET) non-specific cation channel complex located at the tips of the shorter stereocilia of cochlear hair cells and that mediates sensory transduction in the auditory system. The MET complex is composed of two dimeric pore-forming ion-conducting transmembrane TMC (TMC1 or TMC2) subunits, and aided by several auxiliary proteins including LHFPL5, TMIE, CIB2/3 and TOMT, and the tip-link PCDH15. Functionally couples PCDH15 to the transduction channel.
Synonyms: TMHS; MGC33835; dJ510O8.8; DFNB67
Tractability: Antibody: UniProt places it where antibodies can reach, with medium confidence; UniProt predicts a signal peptide or a membrane-spanning region; its Gene Ontology location is reachable by antibodies, with medium confidence.
Gene: Protein-coding gene on chromosome 6 (35,797,206 to 35,845,397, forward strand). Ensembl gene ENSG00000197753.
Subcellular location: Cell membrane
Subcellular location (Human Protein Atlas): Vesicles
Pathways (Reactome):
Sensory Perception: Sensory processing of sound by inner hair cells of the cochlea; Sensory processing of sound by outer hair cells of the cochlea
Gene Ontology:
Molecular function: protein binding
Biological process: detection of mechanical stimulus involved in sensory perception; sensory perception of sound
Cellular component: plasma membrane; apical plasma membrane; stereocilium bundle; stereocilium tip
Genetic constraint (gnomAD): Loss-of-function variants: 12 observed, 19.93 expected, observed/expected ratio (o/e) 0.6, 90% interval 0.38 to 0.98. The upper end of that interval is the gene's LOEUF score, 0.98, which puts it in group 4 of 6, group 1 being the genes least tolerant of losing a copy. Missense variants: 259 observed, 307.62 expected, observed/expected ratio (o/e) 0.84, 90% interval 0.76 to 0.93. Synonymous variants: 111 observed, 126.75 expected, observed/expected ratio (o/e) 0.88, 90% interval 0.75 to 1.02.
Gene-disease validity (ClinGen):
ClinGen rates the evidence that LHFPL5 causes each of these diseases.
nonsyndromic genetic hearing loss (autosomal recessive): Definitive. A disease characterized by hearing loss that is not part of a larger syndrome.
Homologues: Orthologues: chimpanzee LHFPL5 (100% identical), macaque LHFPL5 (100% identical), mouse Lhfpl5 (98% identical), pig LHFPL5 (98% identical), rabbit LHFPL5 (97% identical), dog LHFPL5 (97% identical), rat Lhfpl5 (97% identical), guinea pig LHFPL5 (95% identical), tropical clawed frog fbxl3 (74% identical), zebrafish lhfpl5a (69% identical), zebrafish lhfpl5b (65% identical), Drosophila melanogaster Tmhs (31% identical). Paralogues in human: LHFPL3 (65% identical), LHFPL4 (61% identical), LHFPL6 (25% identical), LHFPL1 (21% identical), LHFPL7 (20% identical), LHFPL2 (19% identical).
Diseases named in the same sentence as LHFPL5 in open-access papers:
LHFPL5 is named in the same sentence as 8 diseases in open-access papers, as found by Europe PMC text mining. Sharing a sentence is not in itself a finding about the gene and the disease. The quoted sentences say what the papers report.
deafness (11 papers, 2014 to 2025). An inherited or acquired condition characterized by the complete loss of the ability to hear from one or both ears. "In humans, LHFPL5 variants are known to cause autosomal recessive deafness, sometimes accompanied by bilateral vestibular areflexia." (PMID 41400044, 2025). "Mutations affecting LHFPL5 lead to autosomal recessive nonsyndromic hearing loss (DFNB67) in humans, and deafness and vestibular dysfunction in mice." (PMID 38194445, 2024). "As LHFPL5 Y127C, C161F, T165M and R176L deafness-causing mutants interact with PCDH153, it is expected that LHFPL5 interacts with components of the MET complex at different sites as well." (PMID 36781873, 2023). "LHFPL5 is a member of the lipoma HMGIC fusion partner (LHFP) gene family and can cause deafness in humans." (PMID 34178671, 2021). "All seven of these families have variants in seven different known deafness genes, LRTOMT, LHFPL5, TMPRSS3, OTOF, MYO15A, ESRRB, and KCNE1." (PMID 31835641, 2019). "In the current study, we detected one reported and six novel mutations in 5 distinct deafness genes (TRIOBP, LHFPL5, CDH23, PCDH15, and MYO7A) in 5 recessive families." (PMID 29568747, 2018). "Of them, 9 deafness genes expressed more in the apical turn (Pou4f3, Slc17a8, Tmc1, Crym, Otof, Ush1c, Pcdh15, Slc26a5, and Lhfpl5) and six were internal controls (Gapdh, Actb, Rps17, Rpl30, Atp6, and Ipo8)." (PMID 24676347, 2014). "This is the first report of a potential LHFPL5‐related inherited deafness in a domestic animal." (PMID 41400044, 2025). "Mutations in LHFPL5 may impair auditory and vestibular function in zebrafish, cause congenital hearing loss in mice, and DFNB67 deafness in humans." (PMID 36781873, 2023). "Interestingly, deafness mutations in LHFPL5 do not affect the interaction of PCDH15 and LHFPL5 and in our structure do not localize to interaction sites of PCDH15 and LHFPL5, suggesting that LHFPL5 interacts with additional components of the mechanotransduction complex." (PMID 30070639, 2018).
hearing loss (5 papers, 2014 to 2025). "The results of gene expression analysis of each cochlear turn showed that 4 ADNSHL genes (Pou4f3, Slc17a8, Tmc1, and Crym) and 9 autosomal recessive non syndromic hearing loss genes (Otof, Strc, Ush1c, Pcdh15, Grxcr1, Dfnb59, Slc26a5, Lhfpl5, and Ptprq) were changed 2-fold or more." (PMID 24676347, 2014). "Furthermore, our study could help direct the clinical diagnosis of hearing loss related to aberrant splicing of TMC1, LHFPL5, and TMIE." (PMID 33509951, 2021).
lipoma (3 papers, 2015 to 2021). A benign, usually painless, well-circumscribed lipomatous tumor composed of adipose tissue. "In mice, lipoma HMGIC fusion partner-like 5 (LHFPL5) acts as an auxiliary subunit of the MET channel whose primary role is to correctly localize PCDH15 and TMC1 to the mechanotransduction complex." (PMID 32009898, 2019).
breast carcinoma (1 paper, 2025). "The most frequently occurring fusion genes in each subtype were TTC6::MIPOL1 in HR+/HER2‒ breast cancers, LHFPL5::CLPSL1 in triple-negative breast cancer (TNBC), and TPTE2::MRPS31P2 in HER2+ breast cancers." (PMID 41213951, 2025). "Our database identified well-known fusion genes that are commonly associated with breast cancer, such as ESR1::CCDC170, and revealed previously unreported fusion genes, including TPTE2::MRPS31P2 and LHFPL5::CLPSL1." (PMID 41213951, 2025).
hypothyroidism (1 paper, 2015). Abnormally low levels of thyroid hormone. "The haplotype contains three genes (LHFPL5, SRPK1 and SLC26A8) with functions that are not explicitly obvious in the development of hypothyroidism." (PMID 26261983, 2015).
nonsyndromic deafness (1 paper, 2018). An auditory system disease that is associated with permanent hearing loss caused by damage to structures in the inner ear and/or the middle ear, which is not associated with other signs and symptoms. "Mutation in the LHFPL5 gene (on chromosome 6p21.31) which is also known as tetraspan membrane protein of hair cell stereocilia (TMHS) gene has been found to cause autosomal recessive nonsyndromic deafness." (PMID 29914565, 2018).
LHFPL5 also shares sentences with these, for which no sentence is quoted: autosomal recessive deafness (1 paper); triple-negative breast carcinoma (1).